VHL (von Hippel-Lindau tumor suppressor)
Diseases named in the same sentence as VHL in open-access papers (continued):
Sharing a sentence is not in itself a finding about the gene and the disease.
tumor (continued). "In addition, mutations in the tumour suppressors BAP1, PBRM1 and SETD2, which co-localise with VHL on chromosome 3p and are frequently disrupted in ccRCC, suppress ISGF3-mediated ISG expression." (PMID 39282259, 2024). "In RCC, the expression of CXCL16 and its cognate receptor CXCR6 also associates with better survival outcomes in patients; however, neither has been linked with VHL loss or tumor-infiltrating lymphocyte (TIL) infiltration." (PMID 38618956, 2024). "MiR-542-5p represented a potential marker of VHL-associated ccRCC that was lowly expressed in normal control urinary exosomes, significantly increased in the preoperative urinary exosomes of tumor-bearing VHL patients, and subsequently reduced to normal levels of expression after tumor excision." (PMID 39062684, 2024). "These in vivo data suggested that FBXO22-mediated VHL degradation can promote GBM tumor growth." (PMID 38519492, 2024). "The HIFs are in turn regulated by oxygen-dependent hydroxylases: both the prolyl hydroxylases (PHDs) which interact with the VHL tumour suppressor and control HIF turnover, and the asparaginyl hydroxylase known as the Factor inhibiting HIF (FIH), which modulates HIF transcriptional activity." (PMID 38690263, 2024). "Additionally, the link between lactylation and VHL gene inactivation has been shown to play a pivotal role in tumor progression." (PMID 39010066, 2024). "VHL operates as a tumor suppressor, diligently guarding against tumorigenesis in ccRCC." (PMID 39796121, 2024). "Following VHL loss, overexpression of HIF-2α is necessary and sufficient for tumor growth." (PMID 38928435, 2024). "Like VHL, mutations of PBRM1 tend to occur early in tumor development." (PMID 37999735, 2024). "Compared to control mice, lung metastases were barely detectable in mice bearing Flag-VHL tumor." (PMID 38914543, 2024). "Approximately 35%–60% of the patients with VHL have bilateral tumours." (PMID 39673085, 2024). "In-silico analysis also revealed that LINC01322 could be involved in regulation of tumor microenvironment during RCC progression by interacting with VHL." (PMID 39886373, 2024). "The VHL protein produced by the gene can inhibit angiogenesis to suppress tumor growth." (PMID 39399506, 2024). "The protein von Hippel‒Lindau (VHL) was originally identified as a tumor suppressor." (PMID 38565887, 2024). "Linkage studies indicate that the VHL gene is a tumor suppressor gene on chromosome 3p25–26." (PMID 39201746, 2024). "Based on in-silico analysis, we hypothesized that LINC01322 could be involved in RCC progression by interacting with VHL, thereby influencing the tumor microenvironment." (PMID 39886373, 2024). "Loss of function VHL mutations result in constitutive activation of hypoxia-inducible factor-2 alpha (HIF-2α), which leads to increased expression of HIF target genes that promote angiogenesis and tumor growth." (PMID 38339352, 2024). "There are other commonly lost tumor suppressors on this chromosome (VHL, SETD2 and PBRM1)." (PMID 39554490, 2024). "Based on in-silico analysis, we also hypothesize that LINC01322 could be involved in RCC progression by interacting with VHL, thereby influencing the tumor microenvironment." (PMID 39886373, 2024). "However, only mice treated with FIH KO OT-I T cells exhibited significantly improved tumour control, whereas VHL KO OT-I and FIH/VHL KO OT-I T cells resulted in equivalent anti-tumour control when compared to WT OT-I T cell responses." (PMID 38690263, 2024). "The identified CK2-SALL2 axis may be part of a broader mechanism where CK2 downregulates the stability of multiple tumor suppressors in the cell, including iκB, VHL, PML, and SALL2, by phosphorylating residues near or within PEST motifs." (PMID 38493149, 2024). "One related study showed that Cyclin D1 promotes tumor growth in VHL-knockout cancer cells in mice." (PMID 39748950, 2024).
tumor (continued). "Partly due to physiological adrenal uptake of 68Ga-DOTA-SSA PET/CT, more tumor specific 18F-FDOPA PET/CT may be preferred in PCCs that are small and/or related to known mutations in NF1, RET, VHL, or MAX." (PMID 38206185, 2024). "Given that JunB had a role in promoting cell invasion and angiogenesis in VHL-deficient RCC, we hypothesize that a close association between this CAFs cluster and tumor invasion." (PMID 38292868, 2024). "VHL/HIF/VEGF pathway is recognized as a key driver in RCC tumor development." (PMID 39886373, 2024). "Furthermore, inhibitors of glutaminase, an enzyme that breaks down glutamine, renders VHL-deficient RCC cells sensitive to glutamine depletion in vitro, blocking tumor xenograft growth in mice." (PMID 36831657, 2023). "The loss of chromosome 3p and VHL and/or PRMB1 mutation in the same epithelial cell may change its behaviour in favour of tumour development." (PMID 37439962, 2023). "Consequently, we conducted a study evaluating mutation and methylation status as well as levels of expression of the VHL gene in tumour samples from 264 patients presenting with PTC." (PMID 36036061, 2023). "The tumor suppressor VHL targets HIF1α and HIF2α earmarked for proteasomal degradation." (PMID 36728187, 2023). "A recently accepted notion of RCC progression is that VHL mutation function as an initial event to drive tumorigenesis, while PBRM1, BAP1 and SETD2 subsequent trigger defects in DNA repair system and abnormal tumor growth." (PMID 37064095, 2023). "While the absence of a driver mutation does not formally allow the conclusion that the tumor is VHL wildtype, it is noteworthy that both multiple (clonal) drivers and VHL wildtype ccRCCs were found to have a poor prognosis in the TRACERx Renal study." (PMID 36562826, 2023). "Furthermore, a statistically significant association was observed between rs1642742 of VHL gene and low pathological tumor stage and between rs779805 of VHL gene and high pathological tumor stage." (PMID 38115281, 2023). "Ion AmpliSeqTM Cancer Panel v1 contains the primers for the VHL gene; however, no VHL mutations were detected in this tumor." (PMID 37273678, 2023). "Somatic VHL mutations on the other hand are rare in histological tumor types not present in VHL disease." (PMID 36036061, 2023). "The VHL protein is highly expressed in normal thyroid follicular tissue and is differentially expressed in non-neoplastic and neoplastic thyroid lesions in proportion to the level of tumor differentiation." (PMID 36036061, 2023). "The VHL gene is a tumor suppressor gene sited on the short arm of chromosome 3 (3p25-26)." (PMID 36611440, 2023). "However, VHL-silenced HER2-CAR-T cells were able to decrease tumour growth significantly, and an improved animal survival relative to NTC-expressing CAR-T cells was seen, clearing tumours in 2 of the 11 animals analysed." (PMID 37166103, 2023). "Von Hippel–Lindau (VHL) is a tumor suppressor gene located on chromosome 3p25." (PMID 36831657, 2023). "However, the difference in the tumor weight between the two VHL-expressing groups was insignificant." (PMID 37762376, 2023). "Such medications target the key factors that are overactive in tumor cells in the context of VHL." (PMID 36980625, 2023). "VHL is an important tumor suppressor that is lost in the majority of ccRCCs." (PMID 37891201, 2023). "Despite this, MIP is a candidate tumor suppressor, while BRCA1 and VHL are known tumor suppressors." (PMID 37742294, 2023). "However, based on the multiple lines of evidence, such as protein stability, hypoxia regulation and tumor growth suppression, we conclude at this juncture that L169P VHL functions comparably to WT VHL." (PMID 37762376, 2023). "Inactivation of VHL in ccRCC leads to constitutive stabilization and activation of HIFα transcription factors, which coordinate numerous cellular activities that contribute to tumor formation and progression." (PMID 36980176, 2023).
tumor (continued). "In addition, a complete genetic analysis of the tumour revealed not only the presence of CHEK2 and VHL mutations, but also the presence of deletions in exon 1 of BRAF-1 and PTEN11, genes involved in tumour development by LOF." (PMID 37843608, 2023). "A strong genetic component is described in these neoplasms, and the most frequent mutations involve succinate dehydrogenase (comprehending A/B/C/D/AF2, collectively called SDHx mutations) and von Hippel-Lindau (VHL) genes." (PMID 37111596, 2023). "Taken together, our findings reveal the previous unrecognized tumor-promoting function of CDK1/PIN1 axis through destabilizing pVHL and provide the preclinical evidence that targeting CDK1/PIN1 is an appealing strategy in the treatment of multiple cancers with wild-type VHL." (PMID 36813923, 2023). "In addition to its interaction with VHL, the tumor-suppressive role of Jade-1 has also been demonstrated through its regulation as a transcription factor of AKT and beta-catenin." (PMID 37175531, 2023). "However, translation is initiated by two methionine residues at amino acids 1 and 54; therefore, VHL proteins of 213 and 160 amino acids (approximately 30 and 19 kDa in size, respectively) are produced, both of which have tumor-suppressing functions." (PMID 36835292, 2023). "As the tumor suppressor VHL protein promotes the ubiquitination and degradation of HIF-2α, we speculated that forced expression of VHL in ccRCC cells might indirectly inhibit the expression of HIF-2α target genes." (PMID 36739418, 2023). "A VHL loss of function leads to the accumulation of hypoxia-inducible factors and the subsequent upregulation of various hypoxia-inducible factor target genes such as VEGF, which drives tumour-associated angiogenesis." (PMID 36803783, 2023). "Consequently, although VHL is the main player in the pathological biology of ccRCC, these other tumor suppressor clusters are also likely to be involved." (PMID 37515929, 2023). "This is associated with bi-allelic inactivation of the von Hippel Lindau (VHL) tumour suppressor, which forms part of an E3 ubiquitin ligase complex that targets HIF-α subunits (HIF-1α and HIF-2α; also known as EPAS-1) for proteasomal degradation in the presence of oxygen." (PMID 36725335, 2023). "Furthermore, the majority of the intravascular VHL+ cells were proliferative (Ki67+), including a pocket of extravasating tumor cells located in the perivascular area." (PMID 37069149, 2023). "However, only the VHL+ tumor cells were able to propagate continually, up to passage 20 currently (data not shown)." (PMID 37069149, 2023). "Under physiological conditions, the VHL protein functions as a tumor suppressor." (PMID 35800063, 2022). "Previous studies have confirmed a progressive decline in the function of these chaperones with aging, which may contribute to the prolongation of missense VHL protein activity and attenuation of the new tumor growth." (PMID 36760665, 2022). "Furthermore, tumor analysis in four VHL patients bearing ccRCC who received propranolol as an off-label treatment for retinal HBs showed a stabilization in tumor growth after three years (on average) of systemic treatment." (PMID 35163250, 2022). "No significant gene mutations, including VHL gene and copy number changes were detected in the tumor using next generation sequencing supporting the diagnosis of sporadic renal hemangioblastoma." (PMID 35220972, 2022). "However, how to transfer the VHL gene safely, efficiently, specifically, and stably to tumor target cells for gene therapy is an urgent problem to be solved." (PMID 35035522, 2022). "VHL inactivation is the earliest event in tumor formation in the majority of sporadic ccRCC cases." (PMID 36413415, 2022).
tumor (continued). "They described three types of tumors presenting different growth patterns: VHL inactivation and chromosome 3p loss had an indolent growth course in comparison to those with PBRM1 mutations, while tumours mutated for both BAP1 and PBRM1 presented rapid progression." (PMID 36551652, 2022). "Xenografting studies reveal that 786-O tumor cells expressing wild-type VHL form tumors with a tightly packed collagen matrix, whereas 786-O cells either without functional VHL or expressing disease variants form tumors with a loose collagen matrix and more extensive blood vessel infiltration." (PMID 36077607, 2022). "Furthermore, we have performed intensive functional and mechanistic study of pathogenicity of these VHL mutants and reveal gain of function for the crucial tumor suppressive VHL protein (pVHL)." (PMID 35505422, 2022). "This includes classical RCC alterations, such as 2pb duplication in the first exon of VHL(c.327_328dupCC) in case of R24 (Grade 4 ccRCC), previously associated with poor overall survival and resistance to therapy in RCC, and the likely driver in this tumour." (PMID 35102500, 2022). "Since a VHL mutation results in unchecked HIF-2α function, glutamine metabolism may be accelerated, promoting growth within the tumor microenvironment." (PMID 35740533, 2022). "VHL targets the chimeric BET degrading agent payload to deliver to the tumor, which may explain the potent killing effect of GNE-987 on AML." (PMID 35958877, 2022). "The limitations of clinical traits (including AJCC stage, Furman score, and pathological grade) and emerging molecular alterations (e.g., VHL, PBRM1 mutation, microsatellite stage, and tumor mutation burden) hinder the capacity to provide optimal clinical management to ccRCC patients." (PMID 38090653, 2022). "Besides, VHL gene-dependent tumor suppression in ccRCC responded to the VHL-mediated ubiquitination process, enabling the possibility of ccRCC treatment through ubiquitination inhibition." (PMID 35538487, 2022). "Decreased gene products associated with VHL mutations lead to increased expression of hypoxia-inducible factor (HIF)-1,2, a hypoxia-inducible factor that enhances angiogenesis into the tumor microenvironment and promotes tumor progression." (PMID 36011051, 2022). "Since surgery remains the only therapeutic option and those repeated surgeries decrease patients’ quality of life, VHL patients demand an effective drug that might halt the tumor progression or delay surgical procedures." (PMID 35457036, 2022). "The higher VHL protein expression was observed in tumor tissue of patients with stage M0." (PMID 35110537, 2022). "Tumours confined to middle ear without involvement of endolymphatic sac and negative for VHL mutation likely represent a subset of adenocarcinoma distinct from ELS tumour." (PMID 35397067, 2022). "This means other family members were positive for the same VHL variants seen in the proband but did not present any tumor or phenotype associated with VHL disease." (PMID 35774415, 2022). "With 52 VHL and 10 KDM5C mutant tumors derived from the TCIA cohort, patients with KDM5C mutations had higher total and visceral abdominal fat content than those with VHL tumor mutations." (PMID 35159060, 2022). "Although no second hits in VHL were detected, copy number calling revealed evidence of 3p loss-of-heterozygosity in all tumor tissues (kidney, adrenal, lung, and liver)." (PMID 35304467, 2022). "The tumor suppressor VHL is lost in over 90% of ccRCCs through genetic or epigenetic mechanisms." (PMID 36077607, 2022). "Thus, in addition to local ECM modification with the formation of an angiogenic niche, the loss of VHL would promote the expression of MMP, which would cause ECM degradation and invasive behavior of the tumor cells." (PMID 36077607, 2022).
tumor (continued). "In addition, miR-155 has also been identified as an oncomiR in various types of human tumors, which inhibits the activity of tumor suppressor targets such as TP53INP1 or the von Hippel–Lindau (VHL) tumor suppressor protein." (PMID 35326471, 2022). "Induction of PIAS4 by hypoxia also causes it to interact with and suppress the tumor suppressor VHL, facilitating its oligomerization, which inhibits its function as a tumor suppressor in HIF1α-dependent and independent manners, contributing to overall tumor progression." (PMID 35887358, 2022). "Loss of function of VHL leads to an accumulation of HIF-α and mimics or aggravates a hypoxic situation in the tumour, leading to an increase in PI3-K/PKB/mTOR signalling and tumour progression." (PMID 36551652, 2022). "This suggests additional pVHL tumour-suppressor functions outside HIFα regulation and implies that activation of HIFα might be necessary, but not sufficient for driving tumorigenesis in the VHL cancer syndrome." (PMID 35760869, 2022). "The physical interaction between VHL and fibronectin, coupled with the diminutive fibronectin deposition by VHL mutant tumor cells, suggest that the cellular phenotype may be explained by an intracellular build-up of unprocessed fibronectin." (PMID 36077607, 2022). "VHL-/- ccRCC tumours and cell lines produce both HIF-1α and HIF-2α or HIF-2α alone." (PMID 36551652, 2022). "The other is that VHL is suggested as mutated as an early event for tumor, and HMGCS2 may have a negative regulation of tumor angiogenesis." (PMID 35479398, 2022). "Furthermore, recent data show that VHL-related ccRCC can be classified into HIF2α-dependent and HIF2α-independent tumours and that these tumours differ in HIF2α levels and in their gene expression." (PMID 35760869, 2022). "The von Hippel–Lindau protein is a tumor suppressor gene involved in the negative regulation of HIF-1α in normoxic conditions, whereas mutations on the VHL gene or hypoxic conditions prevent HIF-1α degradation, which promotes the expression of angiogenic and inflammatory mediators." (PMID 35563616, 2022). "In PPGL lacking SDH/VHL mutations, one metastasis had HIF2αCYT immunostaining as its corresponding primary tumor." (PMID 35740651, 2022). "We found the prevalence of VHL expression in increased tumor growth and metastases development." (PMID 34563045, 2021). "Mechanistic investigations showed that the ATM inhibitor KU-60019 in combination with CX-4945 induced a strong inhibition of tumor cell proliferation, reduction of cell migration and reactive oxygen species (ROS)-dependent apoptosis in HIF-2α-expressing VHL-deficient cells." (PMID 33540838, 2021). "VHL alterations are the most common tumor-initiating event in ccRCC." (PMID 34609963, 2021). "Functional study showed that ARNT2 may inhibit the tumor progression by inducing tumor suppressor gene VHL and inactivating AKT signaling pathway." (PMID 34249704, 2021). "Therefore, the effect of ATM and CK2 inhibition was evaluated on ex vivo tumor slice cultures derived from two VHL− and VHL+ ccRCC PDX models, respectively." (PMID 33540838, 2021). "The HIF pathway drives tumor development and progression in the VHL-inactivated ccRCC." (PMID 33547392, 2021). "Of note, a selective small molecule inhibitor targeting the HIF-2α transcription factor, Belzutifan (MK-6482), has been reported to reduce the size of tumours and inhibited tumour progression in almost 90% of von Hippel–Lindau (VHL) patients over a 3-year study period." (PMID 34572020, 2021). "RCC frequent somatic 3p losses, related to three major RCC tumor suppressor genes, namely VHL (located at 3p25.3), BAP1, and PBRM1 (3p21.1), could have masked germline MITF p.E318K alleles (3p13)." (PMID 34067022, 2021). "Moreover, monogenic VHL mouse models fail to exhibit a renal phenotype and co-deletion of multiple other tumor suppressors on chromosome 3p are known to be required to elicit a phenotype." (PMID 34002003, 2021).